INS (insulin)
Diseases named in the same sentence as INS in open-access papers (continued):
Sharing a sentence is not in itself a finding about the gene and the disease.
type 2 diabetes (continued). "Type 2 diabetes is strongly predictive of the severity of OA, independent of BMI and age32, 33, suggesting the involvement of insulin as type 2 diabetes is an insulin-resistant state." (PMID 28418007, 2017). "Among people with type 2 diabetes, the insulin-treated patients had a much higher incidence than those receiving other types of treatment." (PMID 28824815, 2017). "Thiazolidinediones, such as pioglitazone, are peroxisome proliferator-activated receptor-γ agonists and insulin sensitizers used to treat type 2 diabetes." (PMID 28951826, 2017). "At 26 weeks of treatment, patients with type 2 diabetes randomized to insulin glargine had reductions in mean TG (insulin naïve: −11 mg/dL; prior insulin use: <4 mg/dL); patients with type 1 diabetes had reductions of <2.0 mg/dL." (PMID 28587667, 2017). "Our previous studies have indicated that ultrasound can stimulate the release of insulin from pancreatic beta cells, providing a potential novel treatment for type 2 diabetes." (PMID 29214024, 2017). "It has been demonstrated that an oral aminoacids mixture significantly improves insulin sensitivity in elderly subjects with sarcopenia or type 2 diabetes, probably by an up-regulation of the insulin-receptor synthesis and its autophosphorylation." (PMID 28532453, 2017). "It is expected that inhibition of myostatin function can be an effective alternative approach in enhancing insulin sensitivity and thus for potential prevention and treatment of type 2 diabetes." (PMID 28432282, 2017). "In adipocytes, endocan production is inhibited by insulin and cortisol, and circulating endocan levels have been found to be reduced in overweight and obese women, in insulin resistant and in type 2 diabetes patients." (PMID 28846711, 2017). "Nonetheless, given the presumed link between irisin and the regulation of energy homeostasis and insulin sensitivity, studies are warranted to identify the mechanisms by which irisin impacts human pathophysiology (e.g., type 2 diabetes)." (PMID 28125733, 2017). "In similar fashion, advanced type II diabetes is often presented with chronically low insulin secretion on the background of receding insulin sensitivity, resulting in suboptimal clearance of glucose from the blood." (PMID 28121620, 2017). "The prevalence of celiac disease in type 2 diabetes patients with inappropriate control of glycemia in spite of the insulin therapy, is slightly higher than the actual CD prevalence in general population." (PMID 28985731, 2017). "In type-2 diabetes, both insufficient insulin and excessive glucagon secretion contribute to hyperglycemia." (PMID 28887444, 2017). "Despite this, many national health agencies continue to issue guidelines restricting the use of SMBG in non-insulin treated type 2 diabetes." (PMID 28143495, 2017). "By implication, a GRS derived from T1D can discriminate, to a degree, non-insulin requiring adult-onset diabetes patients with either autoimmune diabetes or T2D." (PMID 28438156, 2017). "In brief, insulin-stimulated 18F-FDG uptake was significantly decreased in a rat model of type 2 diabetes and correlated with transition of BAT to white adipose-like tissue." (PMID 29196742, 2017). "We observed reduced proteinuria in both TA-1887-treated and insulin-treated versus untreated mice, supporting the idea that both TA-1887 and insulin treatments antagonize type 2 diabetes." (PMID 28900540, 2017). "The time course of return of normal first-phase insulin secretion for people with type 2 diabetes during a very-low-energy diet has been defined." (PMID 27817155, 2017). "In insulin naïve patients with type 2 diabetes treated with BIL, there were very few changes, while in those treated with glargine, small LDL and large VLDL decreased from baseline." (PMID 28587667, 2017).
type 2 diabetes (continued). "Because of this, inhibition of dipeptidyl peptidase-IV increases the level of circulating GLP-1, which then stimulates insulin biosynthesis and secretion, which can reverse the hyperglycemic condition in type-2 diabetes." (PMID 28932239, 2017). "In type 2 diabetes, progressive defects of insulin secretion occur, usually against the background of insulin resistance, whereas type 1 (insulin-dependent) diabetes is characterized by autoimmune β-cell destruction and insulin deficiency." (PMID 29084147, 2017). "As an old drug for new use, offers unique approaches for the treatment of type 2 diabetes because of its insulin-sensitizing and anti-inflammatory properties." (PMID 28807030, 2017). "Type 2 diabetes is complex and is characterized by the development of defects in insulin secretion and action, and generally accompanies weight gain, inactivity, and aging." (PMID 28294968, 2017). "Breaking sitting with standing and light-intensity walking effectively improved 24 h glucose levels and improved insulin sensitivity in individuals with type 2 diabetes to a greater extent than structured exercise." (PMID 27904925, 2017). "This compares to incidence rates of emergency medical treatment in the present study of 0.01 events per person per year for all people with type 2 diabetes and 0.037 events per person per year for those with insulin-treated type 2 diabetes." (PMID 28824815, 2017). "Differences in glycaemic, insulin regulation indices, lipids and incretins in fasting and during post-prandial between HNF1α and controls or type 2 diabetes." (PMID 28493909, 2017). "Directly testing the role of insulin reduction in the resolution of obesity and type 2 diabetes following bariatric surgery will need to be addressed in animal models." (PMID 28466412, 2017). "As the insulin tropic action of PPY is preserved in type 2 diabetic patients, this peptide was a candidate as a therapeutic agent for this disease." (PMID 28228865, 2017). "In summary, results from the current study provide an experimental basis for vaspin to be used as a potential insulin-sensitizing and anti-inflammatory agent for islet β cells, bringing new hope for the treatment and prevention of type 2 diabetes." (PMID 29240812, 2017). "Preserving GLP1 via DPP4 inhibition stimulates insulin secretion and has therefore been the recent focus for treatment of type 2 diabetes mellitus (T2DM)." (PMID 29253907, 2017). "Perturbation in insulin signaling pathway, such as insulin resistance impairs hippocampus–dependent memory in humans with type 2 diabetes." (PMID 29258552, 2017). "The infusion of exogenous reconstituted HDL-C potentiated both insulin secretion and skeletal muscle glucose uptake in a small trial with type 2 diabetic patients." (PMID 28372564, 2017). "We took a comprehensive approach to calculate the lifetime risk of the full range of glucose impairments, from normoglycaemia to prediabetes, type 2 diabetes, and eventual insulin use." (PMID 29064009, 2017). "Type II diabetes mellitus, a major constituent of metabolic diseases, is clinically hallmarked by hyperglycemia, impaired peripheral response to insulin (i.e., insulin resistance) and pancreatic β-cell decompensation." (PMID 29326727, 2017). "Together, they point to the importance of functional defects in the insufficient secretion of insulin and excessive secretion of glucagon in type-2 diabetes." (PMID 28887444, 2017). "Also, the browning formation that Irisin may cause could lead to reduced weight gain, up-regulated insulin sensitivity, reduced risk of diabetes type II and other metabolic disorders as animal studies indicate, as well as increase daily resting energy expenditure in humans." (PMID 28620456, 2017). "The pathophysiology of type 2 diabetes is characterized by relative insulin secretory failure against insulin resistance." (PMID 28626771, 2017).
type 2 diabetes (continued). "Recent report based on national data in Denmark between 2005 and 2012 showed that 81% of type 2 diabetes patients received metformin as their first antidiabetic medication, 13% started with sulfonylurea, and 6% with insulin." (PMID 27832382, 2017). "Conversely, removal of excess lipid from the environment of the pancreatic islet allows return of normal insulin secretion in early type 2 diabetes." (PMID 28369092, 2017). "Hypoglycaemia is an unavoidable side effect of insulin therapy in both type 1 and advanced type 2 diabetes and can be life threatening." (PMID 27843452, 2016). "This patient was taking a large amount of soft drinks due to polydipsia before admission, resulting in rapid exacerbation of type 2 diabetes and relative insufficiency of insulin action." (PMID 27652072, 2016). "One hundred and fifty-one obese, insulin-using type 2 diabetes patients were started on GLP-1 RA therapy." (PMID 26597956, 2016). "Differentiating between type 1 and type 2 diabetes is fundamental to ensuring appropriate management of patients, but can be challenging, especially when treating with insulin." (PMID 27080317, 2016). "The aim of the present study is to compare the effectiveness of the addition of metformin to insulin to standard care (insulin alone) in women with type 2 diabetes in pregnancy." (PMID 27435163, 2016). "Pioglitazone increases peripheral insulin sensitivity, enhancing both splanchnic and peripheral glucose uptake, in patients with type II diabetes in randomized, placebo controlled, 12–26 weeks trial." (PMID 27531132, 2016). "Patients diagnosed with type 2 diabetes and receiving continuous insulin therapy, defined by three insulin claims or more, were included in the analysis." (PMID 26759271, 2016). "In obesity or Type 2 diabetes, cellular glucose uptake is often suboptimal due to impaired proximal insulin signaling including IR, IRS and ENPP1." (PMID 27537838, 2016). "In a German general type 2 diabetes population the portion of insulin-based therapies was 31 % which is 20 % lower than in the patients currently studied." (PMID 27286816, 2016). "Given that insulin secretory function can now be returned to normal in type 2 diabetes with re-establishment of normal glucose control, it is now possible to address this question." (PMID 27179658, 2016). "Clinical phenotype has been described with these polymorphisms; type 2 diabetes mellitus (T2DM), cardiometabolic risk factors, obesity indexes, and insulin secretion association were found." (PMID 26839895, 2016). "Because skeletal muscle is responsible for 70%–80% of total insulin-stimulated glucose uptake, skeletal muscle IR is a major determinant of type 2 diabetes." (PMID 26697506, 2016). "Decreased hepatic insulin resistance in type 2 diabetes consistently increased basal levels of insulin receptors and improved insulin signaling defect." (PMID 26459400, 2016). "This computational analysis demonstrates that study of second messenger pathway interactions will improve understanding of critical regulatory sites, how different GPCRs interact and pharmacological targets for modulating insulin secretion in type 2 diabetes." (PMID 27138453, 2016). "In animal obesity models, the phytohormone ABA, related structurally to insulin sensitizers (TDZs) and memory-improvement molecules (such as retinoic acid), ameliorates the symptoms of type 2 diabetes." (PMID 27795733, 2016). "Ethanol and aqueous extracts of PC have an anti-hyperglycemic effect by increasing plasma insulin levels and decreasing blood glucose and total plasma cholesterol levels in type 2 diabetic rats." (PMID 27070585, 2016). "Dysfunction of glucose-stimulated insulin secretion (GSIS) is one of the most important factors in the etiology of type 2 diabetes mellitus (T2DM)." (PMID 27635403, 2016).
type 2 diabetes (continued). "When pancreatic beta cells fail to keep up with the increased needs for insulin, excess glucose builds up in the bloodstream, leading ultimately to type 2 diabetes and various complications." (PMID 26819084, 2016). "We therefore requested data from participants with type 2 diabetes who were insulin-naïve at baseline and data from participants who using insulin at baseline are thus not available to us." (PMID 27537359, 2016). "High doses of insulin (100 IU/ml), such as those seen in cases of type 2 diabetes, also increased IL-6 and decreased TLR2 expression." (PMID 28536605, 2016). "Sensor-augmented pump therapy with automated insulin suspension reduced the combined rate of severe (hypoglycemic seizure or coma) and moderate (hypoglycemia requiring assistance from another person) hypoglycemia in T1DM patients." (PMID 28004007, 2016). "Insulin is a central molecule in pathophysiology of type 2 diabetes and also appears in large number of abstracts related to obesity (23,165 abstracts; 24% of total dataset) in humans." (PMID 26886906, 2016). "We recently have reported the 24-hour glucose, insulin and glucagon responses to a 72-hour fast compared to a 72-hour macronutrient-sufficient, carbohydrate-free diet in men with type 2 diabetes." (PMID 27453716, 2016). "The glucometabolic impairment in type 2 diabetes results from alterations of different signaling pathways modulating glucose uptake comprising insulin- and exercise-induced signaling pathways." (PMID 27069930, 2016). "If the results show improved maternal and fetal/neonatal outcomes using metformin, then physicians treating women with type 2 diabetes in pregnancy will choose to use metformin with insulin as a new standard of care, to reduce serious perinatal morbidity." (PMID 27435163, 2016). "Insulin-resistant states such as type 2 diabetes and obesity are characterised by reduced efficiency of these mechanisms." (PMID 27306890, 2016). "In type 1 and to a lesser extent in type 2 diabetes, the insulin-producing beta cells of the pancreas undergo destruction and exhibit decreased function." (PMID 26822414, 2016). "Destruction and failure of pancreatic beta cells to produce sufficient amounts of insulin to maintain normoglycemia are the main reasons for type 1 diabetes (T1D) as well as type 2 diabetes (T2D)." (PMID 27374092, 2016). "Both postprandial and antecedent nocturnal glucose fluctuations affect daytime frequency-domain HRV parameters in insulin-treated type 2 diabetic women." (PMID 27066358, 2016). "The blood glucose levels were significantly decreased by borapetol B at a dose of 10 μg/100 g in normoglycemic and in type 2 diabetic rats, while the insulin level was significantly increased." (PMID 27047378, 2016). "Partial compensatory hypersecretion characterises individuals within the range of impaired glucose tolerance, while people with the lowest values of insulin secretion often show overt type 2 diabetes." (PMID 27344314, 2016). "Fat deposition in the liver can induce hepatic insulin resistance and precede the development of type 2 diabetes." (PMID 27313625, 2016). "Type 2 diabetes, which is a frequent consequence of obesity, is characterized by chronic hyperglycemia induced by impaired insulin secretion due to decreased β cell mass and function, and increased insulin resistance." (PMID 27965532, 2016). "Failure of pancreatic β-cells to meet insulin secretory demand in the face of diminished insulin sensitivity is fundamental to the pathogenesis of type 2 diabetes." (PMID 27677709, 2016). "In type 2 diabetes there is a well characterised global defect of beta-cell insulin secretory capacity that extends to all insulin secretagogoues including glucose, and particularly GIP." (PMID 27032106, 2016). "Changes in plasma glucose and insulin levels over time resembled the occurrence of a type 2 diabetes (T2D) phenotype, and were consistently more extensive in high-5HT rats." (PMID 26907598, 2016).
type 2 diabetes (continued). "The homeostasis of glucose and other glucose-related metabolites, such as insulin and C-peptide, were the targets for the prevention of metabolic syndrome, such as type 2 diabetes and cardiovascular disease." (PMID 26979433, 2016). "In advanced stages of type 2 diabetes, autophagy in beta-cells occurs due to increased inflammation signals contributing to the decrease in insulin secretion." (PMID 27087124, 2016). "The goal of insulin use in type 2 diabetes is to prevent microvascular and macrovascular complications associated with uncontrolled hyperglycemia." (PMID 27031113, 2016). "Our study is the first to investigate the associations between increased baseline symptom levels of anxiety, depression (and their co-morbidity) and subsequent mortality in a large community-based population of people with insulin naïve Type 2 diabetes." (PMID 27537359, 2016). "Improvements in skeletal muscle size and quality secondary to PRT in type 2 diabetes have been accompanied by reductions in visceral fat and improvements in insulin sensitivity and glucoregulation." (PMID 27175282, 2016). "Compound B has also been shown to induce near-normal insulin secretion in human islets isolated from a donor with type 2 diabetes." (PMID 27100083, 2016). "Other studies have shown the increased expression of TLR2 and TLR4 in conventional insulin resistance target tissues like skeletal muscle and adipose tissue of Type 2 diabetics." (PMID 27478851, 2016). "GLP-1 RA have consistently shown to reduce weight and improve glycaemic control in insulin-using type 2 diabetes patients, however variable responses have been reported." (PMID 26597956, 2016). "A variety of mechanisms contribute to defective insulin secretion and responses in type 2 diabetes, which including glucotoxicity, lipotoxicity, oxidative stress, and the formation of amyloid deposits in the islets." (PMID 27904436, 2016). "Human studies have reported a higher muscle content of ceramide and lower insulin sensitivity in obese and type 2 diabetic patients compared to lean subjects." (PMID 27777958, 2016). "This condition is characterized by an inadequate response of the insulin-sensitive tissues to insulin, leading to type 2 diabetes and metabolic syndrome." (PMID 27995171, 2016). "Insulin level measurement is an acceptable measure to indicate β-cell function in rodent models; our findings are consistent with insulin response pattern in humans with advanced type 2 diabetes, where there is an insufficient insulin secretion to meet demand." (PMID 27774459, 2016). "First phase insulin secretion, which is frequently reduced or lost in patients with long standing type 2 diabetes, is critical in reducing postprandial glucose exertion." (PMID 27455318, 2016). "Decreased insulin secretion has a great impact on the incidence of type 2 diabetes in Japanese subjects." (PMID 27612202, 2016). "Patients with type 2 DM exhibit CCR5 over-expression on their peripheral mononuclear cells, and low-dose infusions of insulin can suppress the expression of CCR5 in mononuclear cells in obese type 2 diabetes patients." (PMID 27553774, 2016). "Insulin-resistant patients can develop type 2 diabetes when there is impairment in β-cells, the result of which is an incapacity to sense glucose properly and release insulin and failed glucose homeostasis." (PMID 27478531, 2016). "Clinicians have described acute severe painful neuropathy occurring during intensive treatment of patients with type 1 and type 2 diabetes treated with oral hypoglycemic agents or with insulin." (PMID 26824041, 2016). "Type 2 diabetes (DM2) is characterized by resistance of insulin-sensitive tissues, such as muscles, liver and fat, to insulin action." (PMID 28035984, 2016). "By using this method, we have previously demonstrated that muscle VATP is reduced in healthy elderly subjects and in insulin-resistant offspring of parents with type 2 diabetes." (PMID 27338702, 2016).